CD27 (CD27 molecule)
Diseases named in the same sentence as CD27 in open-access papers (continued):
Sharing a sentence is not in itself a finding about the gene and the disease.
tumor (continued). "CD27 G2 CAR-T cells had enhanced antigen-stimulated effector functions, upregulated expression of anti-apoptotic proteins (e.g., Bcl-X(L)), increased in vivo persistence, and enhanced tumor regression in an SKOV3 human ovarian cancer cell mouse model compared to G1 CAR T cells." (PMID 35053463, 2022). "Therefore, we hypothesised that CD27, EDA, TNF, TNFRSF12A, TNFRSF13C, and TNFRSF9 may affect tumour prognosis mainly by regulating the TGF-β signaling pathway." (PMID 35392242, 2022). "Given that its receptor CD27 is predominantly found on exhausted T cells (CTL-1), CD70–CD27 interactions may contribute to immune evasion by the tumor." (PMID 36180422, 2022). "However, CD27+ (antiinflammation) and CXCR3+ (tumor trafficking) NK cells were decreased in ALS." (PMID 33974561, 2021). "Additionally, we found that the proportions of total plasma cells (CD19+ CD20+ CD27+ CD38+) and of those secreting IgG and IgM in PDAC were significantly lower than those in the healthy donors, which gradually decreased in higher tumor stages." (PMID 34359579, 2021). "Therefore, maintained L-selectin appears to have a role in the activation of tumor-specific T cells, as indicated by CD44 and CD27 expression at the site of the tumor, but not in tumor-draining LN or spleen." (PMID 31249570, 2019). "Although, CD27+ tumor cells could not be found, over 90% of specimens (38 of 42) showed CD27 expression on TILs adjacent to the tumor cells." (PMID 25951351, 2015). "In 8/8 cases examined, CD27 expression was absent on gated tumor cells, as previously reported." (PMID 24497953, 2014). "In this context the predominantly CD62L+ CD27+ double-positive phenotype of ECAR modified T cells after expansion culture is of interest, as T lymphocytes expressing both surface markers have been described as central memory cells which are able to induce long-term anti-tumor responses in hosts." (PMID 24699869, 2014). "Furthermore, upon transfer into tumor bearing mice Mam-A2 specific CD8 T cells which accumulate and survive longer predominantly become more like an effector memory T cell expressing low levels of both CD62L and CD27 while maintaining high levels of CD127." (PMID 22911764, 2012). "CD70 protein, whether expressed on dendritic cells, B cells, tumour cells, or introduced as soluble protein, promotes the survival and expansion of antigen-primed CD8+ T cells in the mouse, through dose-dependent stimulation of CD27 activity." (PMID 16892042, 2006). "Additionally, CD27 upregulation in this subgroup coincides with that of TRAF2, the canonical adapter of CD27, which was identified as the top hit in a genome-wide CRISPR screen for genes that sensitize tumor cells to T-cell-mediated elimination when CD27 is knocked out58." (PMID 39300154, 2024). "Similarly, tumor PCs (CD19hetCD20hetCD27hetCD38+CD45loCD138+) preferentially showed an increase in expression of B cell marker CD20 and mIg (IgA, IgG, and IgM) in premalignant stages, with downregulation of several markers including CD19, CD27, CD38, and CD45 in both NDMM and RRMM." (PMID 36752202, 2023). "Therefore, CD27, PDCD1, TMIGD2 and TNFRSF25 may participate in tumour immunity by regulating IMCPs." (PMID 37849388, 2023). "In addition, the tumor lysing capacity of CARMz T cells in the mixture of CARMz T and CARP T cells was compromised upon αCD70 treatment in vitro, suggesting that CARP T cells augmented the cytotoxicity of CARMz T cells through the interaction between CD70 and CD27." (PMID 36229619, 2022). "Eight other immune subsets, including naive CD4+ T cells, Lag-3+/−CD8+ T cells and CD14+macrophages, showed no significant enrichment in neither tumour groups, although CD27− B cells with unknown functions were also significantly enriched in tumours with low immune-ITH." (PMID 33431814, 2021).
tumor (continued). "Importantly, the CD27+CD28+ phenotype was more frequently—though variable for each patient with NSCLC—observed in tilTemra, and its presence was largely dependent on a persistent low-grade TCR signal, implying a close relationship with the immunogenicity of tumor antigens." (PMID 34593620, 2021). "Here, we hypothesize a potential anti-tumor immune response of SARS-CoV-2 and based on a computational approach show that: (i) SARS-CoV-2 Spike-RBD may bind to the extracellular domains of CD15, CD27, CD45, and CD152 receptors of cHL or FL and may directly inhibit cell proliferation." (PMID 34696358, 2021). "It was found that the risk score had negative correlation with the BTLA, CD27, CD40, CD80, and TNFRSF14 expression, which had significant differences in different risk groups, indicating that tumor immunosuppression might lead to an increased risk score of patients." (PMID 34899848, 2021). "Their presence has been associated with a reduction in the ability of TIL-B cells to present tumor antigen and positively correlated with the presence of regulatory T cells (Tregs); suggesting the lack of CD27 on TIL-B cells may hinder effective anti-tumor immunity." (PMID 29448960, 2018). "Interestingly, CD27− Vγ6+ γδ17 T cells proliferated extensively in the peritoneal cavity following the transplantation of ID8 ovarian cancer cells, thereby constituting the major source of pro-inflammatory and pro-angiogenic IL-17 that promoted tumor cell growth." (PMID 29750788, 2018). "In our previous work, we had delineated that neoplastic arrest in HCLc most likely occurs at a stage of B-cell differentiation that straddles onset of SHM and deletional CSR, and as HCLc tumour cells do not express CD27, suggests that SHM and CSR may occur at ectopic sites in origins of disease." (PMID 26871591, 2016). "Although the role of NK cells in tumor blood vessels has not been fully studied, it has been pointed out that NK cells in highly invasive and metastatic triple negative breast cancer are mainly immature CD11b-CD27- NK cells, which may be related to tumor metastasis and angiogenesis." (PMID 39847394, 2025). "Most tumor-infiltrating CD8 + T cells are in the early effector memory stage of differentiation, co-expressing CD27, CD28, CD57, and Granzyme B, with little or no perforin." (PMID 39105866, 2024). "The CD138+CD3+ tumor cells also expressed high levels of IGHM, CD27, and XBP1, but were absent of CD19, CD22, CD24, and CD10 expression." (PMID 36494694, 2022). "The tumor infiltrating CD4+ and CD8+ T cells also had a mature immunophenotype, as they were more often CD57 positive and CD27 negative, as well as expressing the chemokine receptor, CXCR4." (PMID 35003893, 2022). "Neither the number of CD8, FOXP3, nor CD27-positive TIL showed difference between CD70-high and low tumor, whereas the number of FOXP3-positive iTIL in CD70-high TSCC was slightly higher than CD70-low (p = 0.07)." (PMID 35145909, 2021). "CD8 + CD57 + T cells in peripheral blood which do not express CD27 and CD28 have enhanced cytotoxic potential, while CD27 and CD28 expressing CD8 + CD57 + T cells in tumor have impaired cytotoxic activity." (PMID 34952595, 2021). "Anti-CD27 did not bind to BCL1, A31, or Eμ-TCL1, and so is not acting as a direct tumor-targeting mAb." (PMID 29198913, 2017). "Spatial transcriptomics of TAMs infiltration in NSCLC reveals that TAMs enrichment in the TME is relevant to tumor cell resistance to ICB immunotherapy regardless of its PD-L1 status, which is mediated by CD27, ITGAM, and CCL5 gene expression upregulation within tumor compartment." (PMID 40083710, 2025). "As expected, CD27 expression was limited to the TME, with no presence on tumor cells." (PMID 40205178, 2025). "The CD27/CD70 axis is an immune checkpoint pathway that has not been fully studied and there is evidence that the CD27 plays an important role as a stimulatory immune checkpoint in tumor progression and cellular immunity." (PMID 38169519, 2024).
infection (184 papers, 2008 to 2025). The state of being infected such as from the introduction of a foreign agent such as serum, vaccine, antigenic substance or organism. "The absence of Prdm1 attenuated ZBTB32 binding to the regulatory regions of Eomes and Cd27 at day 7 post-LCMV-Armstrong infection, and in reciprocal fashion, the Zbtb32-deficiency attenuated Blimp-1 binding (Amp1 in Eomes or Cd27)." (PMID 28827827, 2017). "In wild type hosts the infection-induced mobilization of myeloid progenitors via CCL2/CCR2 resulted in the presence of “CD27+ CMPs” and “GMPs” in the spleen, inversely corresponding to their loss from BM following infection." (PMID 23762028, 2013). "The results showed that infection with B. contaminans was associated with a significant decrease in the number and percentage of B lymphocytes but with a significant increase in the proportion of IgG+CD27+ B lymphocytes." (PMID 36960295, 2023). "However, they did not determine the effect of IL-15/IL-15Rα in the frequency of the different NK cell maturation subsets as determined by CD27 and CD11b expression or the NK cell protective function during a pathogenic infection." (PMID 25399821, 2015). "In addition, CD27 expression has been utilised to discriminate active and latent tuberculosis infection, in which the loss of CD27 expression marks active infection, compared to latent, chronic infection exhibiting high CD27 expression." (PMID 24188324, 2013). "Aside from possible enhanced persistence as a result of possessing low-affinity BCRs, low-affinity IgM+CD27+ B cells may also exist to provide a pool of memory cells with broad antigen reactivity that can counteract immune evasion upon re-infection with antigenic variants of the same pathogen." (PMID 34650561, 2021). "Collectively, these findings establish the "CD27/ICOS-NR4A1-proliferation" axis as a linchpin of PD-1/PD-L1-mediated TRM cell homeostasis, revealing druggable targets for intercepting infection-associated fibrotic progression." (PMID 41262009, 2025). "While the B15/S919+CD8+ T cells had predominantly CD45RA−CD27+ central memory-like phenotype in both prepandemic and post-SARS-CoV-2 infection samples, infection still resulted in a decrease in CD45RA+CD27+CD95- naïve-like B15/S919+CD8+ T cells by 1 mo." (PMID 40892914, 2025). "Compared to vax booster, BA.5.2 infection promoted the percentage of RBD(BA.5.2)+CD19+CD27+ memory B cells." (PMID 39257586, 2024). "Similar results were also observed in the percentage of RBD(BA.5.2)+CD19+CD27+ memory B cells, confirming the reduction of memory B cells in HLA-B*15 individuals after BA.5.2 infection." (PMID 39257586, 2024). "Although the role of CD27+ IFNγ-producing γδ T cells in infection and cancer is well established, the biology of these cells during disease and their adaptation to foreign insult remain poorly elucidated." (PMID 38816652, 2024). "The lack of NFAT signaling in OTI cells resulted in reduced KLRG1+CD27- OTI frequency following acute infection." (PMID 38346075, 2024). "Some other interesting, enriched pathways identified for 3 hours post-infection included Sertoli and germ cell-Sertoli cell junction signaling, CD27 signaling in lymphocytes, IL-17A signaling in fibroblasts, and 5′-AMP-activated protein kinase signaling." (PMID 37615437, 2023). "(I) Quantification of P14 CD43+ CD27+ memory cells by percent of P14 and total numbers in spleen and liver at day 31 post infection." (PMID 38127070, 2023). "This incubation phase is followed by the early acute infection where peripheral plasmablasts (CD27+CD38bright) are transiently yet significantly elevated, as are exhausted cytotoxic T cells (PD-1+)." (PMID 35215797, 2022). "Patients receiving a heterologous booster had a higher proportion of IgM+ SARS-CoV-2 S+ CD19+CD27+ peripheral memory B-cells in comparison to those who acquired infection." (PMID 36232710, 2022).
infection (continued). "While number of total CD19+ B cells was unchanged over time, percentage of CD27+ CD38+ plasmablasts from total CD19+ B cells increased from approximately 0.75% at baseline to more than 15% on day 7 after infection." (PMID 34169553, 2022). "An opposing trend—increase during acute infection—was observed for both the CD45RA+CD38+CD27+ and CD45RA+CD127−CD27+ populations, reminiscent of gradual differentiation into stem cell memory (TSCM) and effector memory (TEMRA), respectively." (PMID 35215797, 2022). "In conclusion, we have found evidence of increased soluble BTLA and TIM-3 as well as CD27 in the immunosuppressed pediatric burn patients who go on to develop infections." (PMID 35958579, 2022). "Only two genes (PTGER2 and CD27) were significantly upregulated in active infection, while the remaining five were downregulated." (PMID 36439147, 2022). "Our results show that both UL40-sepcific and pp65-specific responses belong to TEMRA cells after a primary infection and display a stable CD27-/CD28-, CCR7-, CD45RA+, CD8+ TEMRA phenotype which persist lifelong in HCMV+ healthy hosts." (PMID 36532017, 2022). "CD27+CD127+CD4+ T cells have been previously found in other infection settings and appear to have features of stem-like central memory T (TSCM) cells with self-renewal capacity." (PMID 34128836, 2021). "There was a drop in the percentage of circulating naive/unconventional memory (N/UM) B cells (CD20+ CD38mid CD27− CD10−) ~1 week after infection, but similar changes were observed in control animals." (PMID 33398113, 2021). "The virus induces developmental changes in resting B-cells that mimic germinal center reactions and ultimately memory B-cell phenotype (IgD-CD27+ and IgD+CD27+) where the virus establishes life-long infection." (PMID 34106998, 2021). "In contrast, clusters of CXCR3–CCR6– TH2-like CD25loCD127+ and CD27+ TFH cells were significantly reduced upon infection compared with healthy immune controls." (PMID 34128836, 2021). "After infection, a portion of Bmem cells can be detected with an ‘activated’ phenotype (CD21lo CD27+) and this population has been shown to contract after ~2 weeks." (PMID 33443036, 2020). "Recently, a ratio based on CD27 median fluorescent intensity (MFI) on CD4+ T-cells compared to that on IFN-γ+CD4+ T-cells has been shown to differentiate active disease from infection." (PMID 32131556, 2020). "Previously, CD27 was analyzed as a % or MFI on IFN-γ+CD4+ T-cells of HIV+TB who were not on ART also showed good sensitivity in distinguishing active disease from infection." (PMID 32131556, 2020). "Naïve (CD45RA+ CD27+) CD8+ T cells are depleted from early infection, more so in TP than EC and VC." (PMID 30863403, 2019). "We did find, however, a significant increase in the most mature NK cell population (CD27–CD11b+, Q3) at d2 post-infection in comparison to d3 post-infection." (PMID 31214198, 2019). "Further, the most functional subtype CD27+CD11b+ (stage 3) comparatively decreased at early stages (2, 4 weeks), while increased at middle and late stages (12, 24 weeks) after infection." (PMID 31500589, 2019). "We isolated primary human B lymphocytes from adenoid tissue and sorted the fraction of quiescent naive B cells (IgD+/IgH+, CD38−, CD27−) for our infection experiments." (PMID 31530670, 2019). "Then, we analyzed the distribution of NK subsets based on their CD27 and CD11b expression in WT and iNKT KO mice before and after Cpn infection." (PMID 31236064, 2019). "Despite finding similar numbers of NK cells at days 2 and 3 post-infection, there was a decrease in the proportion of mature CD27–CD11b+ (Q3) NK cells at d3 post-infection in comparison to d2 post-infection." (PMID 31214198, 2019). "The absolute numbers of this γδ T cell subset in blood showed no infection-related changes, whereas the percentages of CD8α+CD27+ γδ T cells within CD2+ γδ T cells in lymph nodes was slightly enhanced in infection groups." (PMID 28559930, 2017).
infection (continued). "Because the persistence of CD10−CD19+CD27+ MBCs were detected in individuals at 9 months recovery from infection, the presence of PvMSP1P-19-specific MBCs was demonstrated in the study." (PMID 28854974, 2017). "During the first 12h of infection, CD27+ CD11b+ NK cells accumulated in the infected mucosa, indicating that NK cells not only increase in abundance, but also display a higher degree of maturation." (PMID 27341123, 2016). "We also addressed the expression of CD27 on influenza virus-specific T cells over the course of the infection and with respect to the cytokines produced." (PMID 27512056, 2016). "Consistent with the similar numbers of LLO-specific memory CD4 T cells in WT and E-FABP-/- mice, LLO-specific memory CD4 T cells in WT and E-FABP-/- mice had similar frequencies of CD27+ cells throughout the infection." (PMID 27588422, 2016). "The percentages of naïve B-cells (CD19+CD27-IgD+) were reduced after infection with wt EBOV or the mutants except the double mutant." (PMID 27930745, 2016). "It has been shown that during acute (Armstrong) or chronic LCMV (clone 13) infection, CD27 initially increases and then returns to the baseline levels with T cells remaining CD27-positive throughout the infection." (PMID 26322025, 2015). "For example, expression of CD62L and CD27 (markers of central memory cells) increases, indicating that the subset composition of the memory population changes with time after infection." (PMID 26485703, 2015). "During acute (Armstrong) or chronic LCMV (clone 13) infection, CD27 initially increases and then returns to the baseline levels with T cells remaining CD27-positive throughout the infection." (PMID 26322025, 2015). "By day 4 after infection, 21.5% (±1.6%) of the NK cells in the mice infected as neonates but only 13% (±0.4%) of the NK cells in adult infected mice were CD11b+ CD27+ (P < 0.01)." (PMID 24173217, 2014). "A significant decrease in the percentage of naïve (CD21+CD27−) splenic B cells was observed at days 28 and 250 after infection (P<0.05)." (PMID 24763747, 2014). "Examining expression of c-Kit and Sca-1 on the Lin−Flt3+CD27+IL-7Rα+ population before and after infection showed that although c-Kit levels were similar, Sca-1 was found to be approximately 10-fold higher." (PMID 24825601, 2014). "At the same time the relative frequency of “CD27− CMPs” (LIN− c-Kit+ CD27−) increased during infection but their absolute number remained unchanged." (PMID 23762028, 2013). "The CD27 antigen is involved in the activation of T cells and plays a role in the infection of T cells by HIV-1." (PMID 23209625, 2012). "In HIV-infected NSG humanized mice, we observed down-regulation of CD27 expression in CD4+ (from 91.25±1.70% positive before infection to 82.00±2.94% at week 6) and CD8+ T cells (from 91.25±1.89% to 77.50±3.11%)." (PMID 22675567, 2012). "Memory B cells (CD27+IgD−) showed enhanced transfer infection compared to total B cells, and were 4- to 5-fold more efficient than naïve B cells (CD27−IgD+)." (PMID 21573183, 2011). "This analysis on day 60 post-infection showed that TemE B5 Tg cells (CD27+, CD62L−) dominated the response." (PMID 21124875, 2010). "A recent study showed that equal numbers of CD45RA+/− CD27− (effector phenotype) and CD45RA− CD27+ (memory phenotype) WNV-specific CD8+ T cells are found one month after infection." (PMID 21179445, 2010). "Similarly, at week 9 and 26 a CD38+CD27+ DN T cells increased significantly in the reinfection (all) group, as well as week 26 in the infection control group." (PMID 40707512, 2025). "To determine the contribution of CD4+ T cells in modulating the formation and activation of IgG+ memory B cell (IgG+ MBC) (CD3-CD20+CD27+sIgG+) populations during a primary DENV2 infection, we measured expression levels of surface IgG in total MBCs via flow cytometry." (PMID 41295476, 2025).